TNF (tumor necrosis factor)
Diseases named in the same sentence as TNF in open-access papers (continued):
Sharing a sentence is not in itself a finding about the gene and the disease.
glaucoma (continued). "Following optic nerve damage and in glaucoma, one proposed mechanism for RGC death is that reactive microglia express proteins that include tumor necrosis factor-⍺ (TNF⍺), interleukin 1⍺ (IL-1⍺), and the complement protein C1q, which together polarize astrocytes to a pro-inflammatory “A1” state." (PMID 36077577, 2022). "However, this protection of anti-TNF is shown only in a rapid, IOP-independent pathway to glaucoma, in which TNF, along with other inflammatory cytokines, is generated anteriorly and causes apoptosis of ganglion cells." (PMID 35651608, 2022). "Previous studies also suggest that during glaucoma macrophages produce cytokines such as IL6, IL1β and TNFα that could lead to an acute inflammatory response." (PMID 35619185, 2022). "Although glaucoma is traditionally considered as a disease that represents RGC death by apoptosis, necroptosis cascades initiated by TNFα from glial activation could also play a role in RGC death in hemodynamically unstable glaucoma patients." (PMID 35396550, 2022). "Additionally, a glaucoma animal model, DBA2J, developed PAS and iris atrophy with age, and the AqH levels of IL-1β, IL-6, IL-10, IFN-γ, TNF-α, MCP-1 and GM-CSF at 50 weeks were significantly higher than those at 8 weeks." (PMID 34830147, 2021). "Taken together, all these results demonstrated that proinflammatory cytokine TNF-α induced the hyperexcitability of RGCs by enhancing Nav1.6 currents and protein expression through activating TNFR1, thus contributing to RGC apoptosis in glaucoma." (PMID 34419081, 2021). "In the DBA2J mice, an experimental glaucoma model that developed PAS at 50 weeks, the AqH levels of IL-2, IL-6, IL-10, IFN-γ, tumor necrosis factor-α, MCP-1 and granulocyte-macrophage colony-stimulating factor (GM-CSF) significantly increased at 50 weeks compared to 8 weeks (p ≤ 0.021)." (PMID 34830147, 2021). "Studies showing increased TNF-α in the aqueous humor and serum of POAG patients suggest that TNF-α may be a potential POAG biomarker, and TNF-α levels could be a marker of glaucoma severity." (PMID 35052396, 2021). "Drawbacks are associated with some; however, for example, oryzanol failed to control IOP in an acute animal model of glaucoma, and lutein is ineffective at reducing increased levels of TNFα in chronic hypoxia." (PMID 34439904, 2021). "In conclusion, reduction in IL-6 would help in reducing the effects of glaucoma as with the other inflammatory cytokines of CXCR4, IL-17, IL-1β, and TNF-α which are known to be increased in PC-12-glaucoma model cells without betalain treatment." (PMID 32666339, 2020). "The usefulness of anti TNF-α therapy in glaucoma will depend upon its ability to block selectively excessive TNF-α and TNF-R1 expression without significantly affecting its physiological functions such as local immunity." (PMID 32774906, 2020). "Our laboratory went on to demonstrate that TNFα increased expression of FasL on microglia in the glaucomatous retina and that the membrane-bound form of FasL was the key effector of RGC apoptosis in an inducible mouse model of glaucoma." (PMID 31570110, 2019). "In the saline injected glaucoma group (group 2), over 5 to 20 fold increase in the messages for TNF-α, IL-1ß and MCP-1 were detected as compared with the non-glaucomatous saline group." (PMID 25923430, 2015). "Similarly, some studies showed that the TNF-α concentrations in AH and/or the ratio of TNF-α positive AH samples in patients with glaucoma was higher than those in controls, which was disclaimed by other studies." (PMID 23559847, 2013). "Here, using a rat model of glaucoma, we investigated the source of elevated TNF- α and examined whether Etanercept, a TNF-α blocker that is in common clinical use for other indications, is protective against RGC death." (PMID 22802951, 2012). "Previous studies have reported elevated levels of TNF-α in the retina and ONH of glaucoma patients." (PMID 22802951, 2012).
glaucoma (continued). "Importantly, in both TNFα triggered RGC death and a spontaneous model of glaucoma, gene-targeted mice that express only full-length FasL exhibit accelerated RGC death." (PMID 21479271, 2011). "Recently, c-jun was found upregulated in glaucoma and optic nerve transaction models, providing evidence of the involvement of c-jun NH2-terminal kinase as a signaling molecule and of the participation of tumor necrosis factor alpha in glaucoma." (PMID 18253094, 2008). "For example, the administration of anti-inflammatory agents such as tumor necrosis factor-alpha (TNFα) inhibitors, minocycline, and FasL-Fas signaling inhibitors led to lower immune cell infiltration and reduced axonal degeneration and RGC death in rodent models of glaucoma." (PMID 39738875, 2025). "Early elevation of pro-inflammatory cytokines (specific factors not identified) is speculated to involve TNF-α, IL-1, and IL-6, influencing the neuroinflammatory process in glaucoma." (PMID 40486511, 2025). "Additionally, DLG4 (discs large MAGUK scaffold protein 4) and several proinflammatory chemokines and cytokines already known to have a role in glaucoma, e.g., C-X-C motif chemokine ligand 8 (CXCL8), tumor necrosis factor (TNF), and interleukin-6 (IL-6), were other central nodes in the network." (PMID 39458974, 2024). "In this study, we showed that TNF-α-mediated Nav1.6 upregulation was a major factor for RGC hyperexcitability and injury in glaucoma, suggesting that sodium channel blockers selectively targeting on Nav1.6 may be a potential therapeutic strategy in the treatment of glaucoma." (PMID 34419081, 2021). "TRPV4 activation induces Müller cell gliosis and TNF-α elevation via the JAK2/STAT3/NF-κB pathway, which may exacerbate RGC apoptosis in glaucoma; these results suggest that TRPV4 can serve as a therapeutic target in glaucoma treatment." (PMID 34789280, 2021). "In this study, we demonstrated that TNF-α could induce RGC hyperexcitability, as evidenced by increased spontaneous firing and evoked AP frequencies of the cells, thus contributing to RGC injury in glaucoma." (PMID 34419081, 2021). "In addition, TRPV4 activation could directly lead to the release of inflammatory factors, particularly TNF-α, which participates in RGC apoptosis in glaucoma." (PMID 34789280, 2021). "Finally, TRPV4 inhibition led to reduced Müller cell reactivity, as well as lower overall levels of GFAP expression, TNF-α release, and RGC apoptosis; these findings implied that TRPV4 activation-mediated inflammatory factors were involved in RGC apoptosis in glaucoma." (PMID 34789280, 2021). "Here, normotensive eyes showed no upregulation of IL-1α, TNF-α, and C1q proteins, suggesting that if present, microglial reactivity in the control eye may not result in A1 astrocyte activation in this model of glaucoma." (PMID 33147455, 2020). "Another group found the levels of IL-8, TGFβ-1, TNF-α, and SAA to be significantly increased in POAG and pseudoexfoliation glaucoma (PEXG) patients compared with controls, while levels of IL-6 were significantly decreased in both glaucoma groups compared with controls." (PMID 29675026, 2018). "In chronic optic nerve damage conditions, such as glaucoma, the phenomenon of secondary degeneration is less apparent; however, RGC survival in experimental glaucoma was also improved by treatment with minocycline and with the TNFα decoy receptor, Etanercept, or in mice lacking the Tnf gene." (PMID 27126275, 2016). "TNFα is expressed by a number of innate immune responders, and has been co-localized to optic nerve head, nerve fiber layer, GCL, and the inner nuclear layer of human glaucoma patients, and is upregulated by macroglia and microglia in the optic nerve and optic nerve head." (PMID 25407441, 2014).
glaucoma (continued). "In the present study, we use an antibody microarray approach to examine the patterns of pro-inflammatory proteins such as INF-γ, TNF-α, several interleukins and protein levels of the complement cascade in retinal samples obtained from human donor eyes with or without glaucoma." (PMID 23451242, 2013). "TNF-α and its receptor have been detected in the ONH of glaucoma patients and in a rat model of glaucoma, suggesting that TNF-α may be an important factor in the neurodegenerative process of glaucoma." (PMID 22802951, 2012). "It has been observed that both mRNA and protein levels of TNF-α or TNF-α receptor-1 (TNF-R1) are raised in the retina of glaucomatous eyes as compared to normal eyes, and therefore it was suggested that cell death mediated by TNF-α is a contributing factor in the neurodegeneration in glaucoma." (PMID 20029655, 2009). "Indeed, as a consequence of glaucoma-related harmful stimuli (including optic nerve injury, IOP elevation, and excitotoxicity), reactive glial cells redistribute throughout the retina and the optic nerve, where they start producing inflammation mediators such as IL-6 and TNF-α." (PMID 38337691, 2024). "This indicates that TNF-alpha may not directly influence the IOP or severity in glaucoma." (PMID 37511830, 2023). "We found that TNF-α production was increased by TRPV4 activation in MIO-M1 cells and decreased by statins, implying that statins could be therapeutic agents with neuroprotective effects for glaucoma patients, if proven by animal models, which will be our next research project." (PMID 35563594, 2022). "Elevated levels of TNF in ocular biofluids (aqueous humor) and plasma are measurable in primary open-angle glaucoma (POAG) patients, the most prevalent type of glaucoma, compared to non-glaucomatous individuals." (PMID 39448868, 2025). "Although there are no preclinical studies for TNFR selective drugs in glaucoma, multiple observations from other neurodegenerative diseases such as AD indicate that this approach could provide neuroprotective effects while minimizing the side effects of global neutralization of TNF." (PMID 35651608, 2022). "In addition, TRPV4 activation could enhance the release of inflammatory cytokines (e.g., tumor necrosis factor-α [TNF-α]) through JAK2/STAT3/NF-kB signaling pathways in Müller cells and elevated expression of TNF receptor 1 in RGCs; this process is involved in RGC apoptosis during glaucoma." (PMID 34789280, 2021).
type 1 diabetes (203 papers, 2008 to 2026). "Type 1 diabetes is characterized by elevated levels of pro-inflammatory cytokines, such as IL-6, TNF-α, and IL-1β, typically transient and linked to the acute immune response against the virus." (PMID 39861189, 2025). "Notable genes included RHOA that is involved in cytoskeletal dynamics, cell cycle, and cell migration, and the multifunctional proinflammatory cytokine TNF, which is also a type 1 diabetes susceptibility gene." (PMID 40113970, 2025). "Inflammatory cytokines, such as tumor necrosis factor alpha (TNFα) or different interleukins (ILs), trigger chronic low-grade inflammation that is linked to the development and progression of type 1 diabetes." (PMID 36982878, 2023). "Interferon-gamma (IFN-γ), TNF-α, and IL-1β are closely associated with the development of type I diabetes." (PMID 36386181, 2022). "It is well-established that pro-inflammatory cytokines, such as interleukin-1β (IL-1β), interferon-γ (IFNγ) and tumor necrosis factor-α (TNFα), are major candidates for causing apoptotic death of pancreatic β cells and immune-mediated diabetes." (PMID 31130919, 2019). "In animal model of type 1 diabetes, macrophages of Gal-3 deficient mice produce less TNF-alpha and nitric oxide (NO) and are less effective in intracellular and extracellular killing compared with WT mice." (PMID 27057168, 2016). "To investigate whether DSG2 supports islet survival, we challenged isolated islets with the cocktail of pro-inflammatory cytokines implicated in the development of type 1 diabetes; namely TNFα, IL-1β, and IFNγ." (PMID 36309486, 2022). "TNF-α also accelerates cartilage loss during fracture healing in type 1 diabetes rats or mice." (PMID 29240821, 2017). "In the current study, we have found almost similar TNF-α -238G/A and -308G/A allele frequencies from North Indian population in studies related to Mycobacterium tuberculosis infection and Type-1 Diabetes." (PMID 24837009, 2014). "Type 1 diabetes caused a significant increase in the mean fold change in the relative mRNA expression of the renal proinflammatory markers such as nuclear factor-κB NFKβ, tumor necrosis factor (TNFα), interleukin-1β (IL-1β), and interleukin-6 (IL-6) compared with the control group." (PMID 38044936, 2023). "Specifically, immunoglobulin 6 (IG-6) and TNF-α are potent proinflammatory cytokines that are significantly increased in patients with gingivitis and type 1 diabetes." (PMID 40141192, 2025). "KEGG pathway analysis identified enrichment in 227 pathways, with natural killer cell-mediated cytotoxicity, type I diabetes mellitus, and TNF signaling pathway showing particularly significant enrichment." (PMID 40646807, 2025). "In a study analyzing patients with type 1 diabetes, a significant reduction in TNF-α levels in crevicular fluid in the group treated with aPDT was observed." (PMID 40710134, 2025). "Available data on the relationship between TNF-α and glycemic control in type 1 diabetes are somewhat conflicting." (PMID 38542165, 2024). "Our findings demonstrated that the concentration of TNF-α was markedly elevated in the cohort of patients with type 1 diabetes when compared to the control group." (PMID 39273664, 2024). "Monoclonal cell populations were treated with proinflammatory cytokines (interleukin-1β, interferonγ, and tumor necrosis factor α) to model type 1 diabetes in vitro." (PMID 39342996, 2024). "The cytokines interleukin-1β (IL-1β), interferon-γ (IFNγ) and tumor necrosis factor-α (TNFα) are the main mediators of beta-cell death and are commonly used in vitro as a model of type 1 diabetes pathogenesis." (PMID 37113489, 2023). "The production of TNF in the early stage of type 1 diabetes contributed to its progression, while the appearance of cytokines in the later stage of the disease was associated with a decrease in the number of autoreactive lymphocytes." (PMID 36768715, 2023).
type 1 diabetes (continued). "In type 1 diabetes, most studies have focused predominantly on the release of the cytokines IL-1β, TNFα and IFNγ, and their role in beta cell damage." (PMID 37762318, 2023). "Both psoriatic disease and type 1 diabetes are affected by chronic inflammation-related cytokines such as tumor necrosis factor, IL-1, and IL-654." (PMID 37798369, 2023). "In type 1 diabetes, levels of IL-6 (p = 0.030) and TNF-α (p = 0.019) were increased in males compared to females." (PMID 37189645, 2023). "In the treated type 1 diabetes mouse model, serum TNF-α, IL-12, and IFN-γ secretion were greatly reduced in the OI group, whereas CXCL1 and IL-10 production was restored." (PMID 36918798, 2023). "It was also shown that golimumab, a monoclonal antibody against TNFα can have beneficial effects on endogenous insulin production and exogenous insulin requirements in children and young adults with newly diagnosed type 1 diabetes." (PMID 37180128, 2023). "In studies about the complications of type 1 diabetes, the expression of TNF-α in the plasma of patients with proliferative retinopathy is remarkably increased." (PMID 35711530, 2022). "In mouse and rat models of type I diabetes, TNF-α neutralization has been shown to attenuate the DCM, as evidenced by the reduction of intramyocardial inflammation and cardiac fibrosis." (PMID 35163209, 2022). "A total of 216 DEGs directly or indirectly related to type I diabetes mellitus, natural killer cell-mediated cytotoxicity, Th1, and Th2 cell differentiation, and the IL-17 and TNF signaling pathways were obtained." (PMID 35534828, 2022). "Administration of a PGE2 receptor EP4-selective agonist increased TNF-α (an inflammatory cytokine) levels and exacerbated renal fibrosis in an animal model of type 1 diabetes." (PMID 36438844, 2022). "Studies have found that the expression of TNF-α is significantly increased in the kidneys of rats with type I diabetes." (PMID 35299891, 2022). "IFN-γ, IL-1β, and TNF-α production by autoreactive Th1 cells is involved in the destruction of insulin-secreting β-cells in type 1 diabetes." (PMID 35652039, 2022). "The elevated expression level of TGF-β1 and TNF-α has a strong correlation with the pathogenesis of type I diabetes." (PMID 36714129, 2022). "It is known from the literature that the main ways of the destruction of beta cells, decreased synthesis, and secretion of insulin in type 1 diabetes is largely determined by the influence of ROS and TNF-α." (PMID 34572994, 2021). "In the present study, a distinct gut region-dependent TNFα induction was revealed in type 1 diabetic rats and segment-specific effects of immediate insulin treatment on TNFα expression was also observed." (PMID 34572059, 2021). "Blockade or antagonism of the central proinflammatory cytokine TNF-α using infliximab, adalimumab or the receptor fusion protein etanercept have shown some potential in type 1 diabetes, with indications of improved glycaemic control and C-peptide secretion." (PMID 33595677, 2021). "More recently, a C-peptide-sparing effect of TNF-α blockade was reported with golimumab use, after 1 year in children and young adults with type 1 diabetes." (PMID 33595677, 2021). "During the initial stage of type 1 diabetes, prolonged exposure of pancreatic β-cell to proinflammatory cytokines such as IL-1β, TNF-α, and IFN-γ results in a decreased capacity to produce and release insulin, as well as cell loss by apoptosis." (PMID 34054343, 2021). "The development of type 1 diabetes also largely depends on proinflammatory cytokines (IL-1, tumor necrosis factor (TNF), interferon (IFN)) are also mediators of islet β cell dysfunction and apoptosis." (PMID 33153226, 2020). "For example, TNF-α has been found to be elevated, unchanged, as well as decreased in type 1 diabetes." (PMID 33042112, 2020). "It has previously been shown that systemically increased TNF-α levels are present in type 1 diabetes with increased blood pressure or cardiovascular disease." (PMID 32908447, 2020).